CRP (C-reactive protein)
Diseases named in the same sentence as CRP in open-access papers (continued):
Sharing a sentence is not in itself a finding about the gene and the disease.
Arthritis (continued). "We showed that a gradual increase in CRP over almost 10 years was associated with subsequent impairment in balance, walking speed, lower body strength, and ADL- and IADL-related disability and arthritis, after taking into account arthritis and disability at baseline." (PMID 29462285, 2019). "The cited SpA features include inflammatory back pain, arthritis, uveitis, heel enthesitis, dactylitis, psoriasis, inflammatory bowel disease, good response to non-steroidal anti-inflammatory drugs (NSAIDs), and family history of SpA, HLA-B27, and elevated C - reactive protein (CRP)." (PMID 30206560, 2018). "A similar analysis against mental unhealthy days showed the association of CRP classes and BMI groups to be non-significant, although significant associations were observed for presence of asthma, presence of arthritis, current smoking status, occurrence of any heart disease and gender." (PMID 30123515, 2018). "This is because change in CRP was not related to arthritis risk." (PMID 28604559, 2017). "However, the indirect pathway from CASP-19 intercept (via CRP intercept) to arthritis risk was no longer significant (p = .057)." (PMID 28604559, 2017). "CRP slope was not a significant predictor of arthritis risk." (PMID 28604559, 2017). "Furthermore, it proposes for consideration/reconsideration the assessment of IL-6 and other markers of arthritis including systemic autoantibodies and, as proposed previously, C-reactive protein for monitoring the disease and therapy response in ovarian cancer." (PMID 27527602, 2016). "However, this topic is still controversial, as the capability of metabolomics to measure the inflammatory status of RA has been demonstrated in a recent study, in which patients with early arthritis were stratified by 1H-NMR metabolomics according to the levels of serum CRP." (PMID 26558759, 2015). "Moreover, in animals treated with QFGJS, it was found not only to suppress proteins expressions related to the pathogenesis of arthritis but even activate expression of some proteins like Vim vimentin, C-reactive protein, and Np purine nucleoside phosphorylase." (PMID 23781264, 2013). "If we were to expand the set of most important features beyond the four basic ones (arthritis, oral ulcers, albumin, and anti‐DNA), the important candidates would be PT, ALT, CRP, creatinine, and ESR." (PMID 41583997, 2026). "High CRP levels are seen in a number of SLE scenarios, for example, in cases of serositis or arthritis; thus, the interaction of CRP and C1q would be a more classical process." (PMID 40801960, 2025). "Computer-aided molecular design database predictions revealed complex interactions between CRP, OST, and PADI4, highlighting their roles in arthritis pathogenesis." (PMID 40266392, 2025). "CRP POCT results should be interpreted with caution in patients with existing conditions that can elevate CRP values (eg, arthritis, gout, IBD) and in those receiving immunotherapy." (PMID 40436444, 2025). "This is in contrast to traditional biomarkers like CRP or ESR, which lack specificity for arthritis." (PMID 41296710, 2025). "At the onset of arthritis, elevated erythrocyte sedimentation rate (ESR) was documented in most cases (in 18/25, 72.0%, patients in which was available), as were elevated C-reactive protein (CRP) levels (in 20/26, 76.9%, patients in which was available)." (PMID 41287064, 2025). "His levels of CRP and ESR were low at the 9-month follow-up, but these levels subsequently increased, as did the symptoms of arthritis." (PMID 40909428, 2025). "C-reactive protein (CRP), a key inflammatory marker for arthritis, has been found to have a positive correlation with the prevalence of PD in studies." (PMID 39234184, 2024). "Recent research has demonstrated that treatment with naringenin after the onset of collagen-induced arthritis can alleviate arthritis symptoms by modulating the levels of the cytokines IFN-γ and IL-17, myeloperoxidase, nitric oxide, and C-reactive protein." (PMID 39086864, 2024).
Arthritis (continued). "Patient 5 experienced disease flare manifesting with fever, rash and arthritis with elevated level of ESR and CRP when canakinumab treatment was prolonged to once every six weeks." (PMID 38550627, 2024). "The C-reactive protein (CRP) and the erythrocyte sedimentation rate (ESR) are inflammatory markers elevated in the acute phase of arthritis." (PMID 38765271, 2024). "AHR, CAV1, CRP, CXCL2, IRF1, SPP1 and other targets play important roles in the pathogenesis of arthritis and can be used as key targets for the treatment of arthritis." (PMID 37637408, 2023). "When arthritic rats were given Nano ZT/Vit B12, their serum levels of RF, CRP, TNF- α, IL-1β, and IL-17 decreased significantly (p ˂ 0.05) when compared to the arthritis group." (PMID 37259429, 2023). "Key ML classifiers included disease duration, blood lymphocyte percentage, neutrophil percentage, neutrophil-to-lymphocyte ratio, gender, C-reactive protein (CRP) levels, shawl sign, arthritis/arthralgia, V-neck sign and anti-PM-Scl75 antibodies." (PMID 38243695, 2023). "The top 10 were disease duration, percentage of lymphocytes (L%), percentage of neutrophils (N%), neutrophil-to-lymphocyte ratio (NLR), sex, C-reactive protein (CRP), shawl sign, arthritis/arthralgia, V-neck sign, and anti-PM-Scl75 antibodies." (PMID 35237262, 2022). "Panel D-F, both SAP (the murine counterpart of CRP), IL-6 and TNF-α were significantly elevated after induction of arthritis." (PMID 35077491, 2022). "Anthropometry indices, body composition, lipid profile, C-reactive Protein (CRP), Malondialdehyde (MDA), and the Western Ontario and McMaster Universities Arthritis Index (WOMAC) were assessed at the baseline condition and after 12 weeks." (PMID 33596883, 2021). "Mucosal ulcers and arthritis waxed and waned with fluctuating inflammatory markers such as erythrocyte sedimentation rate (ESR) and C-reactive protein (CRP)." (PMID 34249981, 2021). "Her daughter's dermatitis, mucosal ulcers, arthritis, and headaches had also improved, and ESR and CRP levels were normal." (PMID 34249981, 2021). "After correction for multiple testing, the ZFP90 expression levels were related to serositis (FDR p = 0.004), arthritis (FDR p = 0.020), hematological involvement (FDR p = 0.021), and increased C-reactive protein (CRP) (FDR p = 0.005) in cases." (PMID 33796098, 2021). "Her rash, arthritis, and ophthalmitis significantly improved, and the acute phase reactants ESR and CRP decreased to normal range." (PMID 34745107, 2021). "TCZ can quickly relieve fever and inflammation (indicated by decreased CRP and ESR), especially for patients showing less active arthritis in the early stage." (PMID 34820342, 2021). "The between-groups analysis of covariance showed a significant effect on the Western Ontario and McMaster Universities Arthritis index (WOMAC) scale (p = 0.000) and CRP (p = 0.022)." (PMID 33297347, 2020). "SM significantly alleviated arthritis symptoms, inhibited bone erosion, and decreased the levels of TNF-α, IL-1β, CRP, ATX, and LPA in the sera of CIA rats." (PMID 31001354, 2019). "SM significantly improved arthritis symptoms; increased the level of OPG; inhibited the levels of TNF-α, IL-1β, CRP, ATX, and LPA; and alleviated cartilage and bone injury." (PMID 31001354, 2019). "Age, CRP, FPG and medical history of arthritis were significantly greater in DMS participants than in non-DMS, however, BMI was significantly lower in DMS group." (PMID 30533044, 2018). "We assessed arthritis score; production of TNF-α, IL-6, and CRP in serum; and histological changes of ankle joints." (PMID 27900440, 2018). "On the other hand, RF levels in the non-RRP group did not correlate with either IgG or IgA index values, and furthermore either arthritis or inflammatory marker levels, although RF levels correlated well with ESR, CRP, and anti-CCP antibody levels." (PMID 29408886, 2018).
Arthritis (continued). "To understand the possible influence of levels of inflammation on the observed differences in global 11β-HSD1 activity between different groups of early arthritis patients, we compared the levels of ESR and CRP in these groups." (PMID 25971255, 2015). "In the antibacterial treatment cases (14 cases of PJI and 5 cases of pyogenic arthritis), the preoperative median WBC counts and median CRP levels were 5,670/mm3 (range, 3,630–8,690/mm3) and 0.2 mg/dL (range, 0.0–2.6, reference value 0.3), respectively." (PMID 26583103, 2015). "In our second case, the pattern of lower limb large joint asymmetrical arthritis, ILBP, erythematous plaques suggestive of psoriasis, elevated CRP, and radiological sacroilitis suggested the initial diagnosis of SpA." (PMID 25431725, 2014). "Even acute-phase response (erythrocyte sedimentation rate (ESR), C-reactive protein (CRP)), which is the hallmark of inflammation, is not a reliable biomarker in BD and elevated only in relation to a limited number of disease manifestations, such as arthritis or some skin lesions of the disease." (PMID 23336215, 2013). "Other correlations areinsignificant between the period arthritis persists on the one hand and erythrocyte sedimentationrate(ESR)/C-reactive protein(CRP) on the other." (PMID 20107565, 2009). "Our findings highlight arthritis, followed by oral ulcers, albumin, and anti‐DNA, which significantly impact the model as highly relevant features, alongside several others such as PT, ALT, CRP, creatinine, and ESR." (PMID 41583997, 2026). "Although this speculation is based on an animal arthritis model study, elevated LRG concentrations in moderate to severe disease itself might promote CRP production via IL-6 and also by T helper 17 cell differentiation." (PMID 39823192, 2025). "The interaction between CRP, OST, and arthritis, specifically involving PADI4 (Peptidyl Arginine Deiminase 4), is an area of research focused on understanding the pathogenesis of arthritis." (PMID 40266392, 2025). "A 9-year-old boy presented with a 3-month history of knee pain and swelling, initially attributed to a femoral non-ossifying fibroma and arthritis based on computed tomography findings and slightly elevated C-reactive protein levels." (PMID 39941211, 2025). "CRP, an acute-phase protein primarily induced by interleukin-6 (IL-6) during inflammation, typically remains below 60 mg/L in active SLE (except situations of serositis, arthritis, or myositis) but is higher in active versus inactive SLE." (PMID 40988967, 2025). "In arthritis patients, chronic inflammation leads to persistently elevated CRP levels compared to non-arthritis individuals, suggesting its potential role as a predictor of mortality risk." (PMID 39980916, 2025). "While disease severity is quantified with C-reactive protein and physical examination findings, many of the outcomes are patient-reported without accompanying pathologic or imaging data on the arthritis severity." (PMID 40042325, 2025). "Women in the latest inception cohort had lower average CRP, less radiographic arthritis, and less angina at baseline, and this trend did not extend to male patients with RA." (PMID 40470043, 2025). "Patients with CRP ≥ 10 mg/L, Ro52 (+) and RPILD may be related to a shorter survival time, while patients complicated with arthritis may present with relatively mild conditions." (PMID 38934403, 2024). "In conclusion, the evaluation of ADA, CRP, UA, and RF levels offers significant perspectives on distinguishing between individuals with and without arthritis." (PMID 38699124, 2024). "This is highly relevant given that both CRP and ESR often fall within the normal range despite the presence (or likely future development) of clinical signs of disease activity, such as uveitis or clinical arthritis." (PMID 38962573, 2024). "In untreated psoriasis patients without arthritis, CRP can be interchanged with PASI as a measure of disease severity." (PMID 39328313, 2024).
Arthritis (continued). "Studies that analyze and compare the levels of uric acid, ADAs, CRP, and RF in patients with and without arthritis." (PMID 38699124, 2024). "Patients with arthritis had a median CRP concentration of 2.60 mg/L compared to 1.50 mg/L for patients without arthritis." (PMID 38256249, 2024). "The limitations of the CHIK-DAS with and without CRP include the need for further validation in additional cohorts with longer and shorter durations of arthritis to see how robust the metric is in different populations." (PMID 40365468, 2024). "Overall, patients with LEI > 0 or patients with SPARCC > 0 had higher mean baseline C-reactive protein (CRP) (8.3–19.7 mg/L) and arthritis pain (VAS) scores (44.2–62.8), compared with patients with LEI = 0 and SPARCC = 0 (7.1–9.8 mg/L and 45.9–51.0, respectively)." (PMID 37608391, 2023). "C-reactive protein and sedimentation rate, which are indicators of inflammation, were statistically higher in patients with arthritis than in those without." (PMID 37403914, 2023). "This association still exists after adjustment for age, gender, race/ethnicity, smoker, BMI, eGFR, UACR, serum C-reactive protein, WBC count, NLR, serum calcium, arthritis, aspirin use, calcitonin use, biphosphonate use, DMARDs use, calcium intake and estrogen use." (PMID 37154137, 2023). "Second, it was difficult to recognize arthritis in patients without fever, or re-elevation of CRP, especially in infants." (PMID 37336934, 2023). "Several studies have reported that C-reactive protein (CRP), leukotriene B4 (LTB4), prostaglandin E2 (PGE2), interleukin 6 (IL-6), and tumor necrosis factor-alpha (TNF-α) play crucial roles in inflammatory processes and the pathophysiology of arthritis." (PMID 36046031, 2022). "Localization and prevalence of joint effusion and arthritis in CRP+ and CRP− patients." (PMID 36743676, 2022). "On evaluation, she had active arthritis of the right knee, ankle, wrist, and left elbow, with laboratory test results showing a CRP of 15, negative RF, anti-citrullinated peptide antibody (ACPA), and antinuclear antibodies (ANA)." (PMID 36199642, 2022). "Clinical examination revealed no frank arthritis and the laboratory tests showed only a high CRP (14mg/dl - normal values <6) and high ESR (48mm/h)." (PMID 35611100, 2022). "As such, the first objective of this study was to evaluate the effect of oral L-carnitine supplementation on CRP, MDA, lipid profile, Western Ontario and McMaster Universities Arthritis Index (WOMAC), as well as anthropometry and body composition measures in obese women with KOA." (PMID 33596883, 2021). "Another decoction named Qianghuo Erhuang can significantly decrease the disease activity score in 28 joints (DAS28), erythrocyte sedimentation rate (ESR), and C-reactive protein (CRP) in RA and upregulate the percentage of Tregs in adjuvant-induced arthritis in rats." (PMID 34512345, 2021). "Some studies identified an association between CRP or ESR and arthritis development, while others did not." (PMID 34211986, 2021). "After 6-months of therapy, her fevers, skin lesions, oral and genital ulcers, arthritis, headache, and dizziness alleviated, no uveitis occurred, CRP decreased to the normal level." (PMID 34249981, 2021). "Disease activity was defined as the presence of at least one of systemic symptoms (fever, rash, lymphadenopathy, hepatosplenomegaly, serositis, sore throat) and/or arthralgias/arthritis and at least one abnormal laboratory marker (hematological profile, ESR, CRP, ferritin, liver enzymes)." (PMID 34868356, 2021). "Clinical features of HIDS are similar to those of hereditary periodic fever syndromes, which include recurrent fever, lymphadenopathy, hepatomegaly, rash, arthritis, abdominal pain, and increased levels of biomarkers like serum amyloid A (SAA), serum IgD and C-Reactive Protein (CRP)." (PMID 32822427, 2020).
Arthritis (continued). "The 4C-DAS28 is a composite score of a 28 swollen and tender joint count (SJC and TJC), a visual analogue score (VAS: 0–100mm) of patient global assessment of arthritis activity and an objective biochemical marker of inflammation erythrocyte sedimentation rate (ESR) or C-reactive protein (CRP)." (PMID 33124499, 2020). "On presentation, she was febrile (38°C) and had high ESR and CRP levels, but most of her laboratory tests were within normal levels and had no signs of arthritis or rash." (PMID 32185342, 2019). "To obtain a clear picture of the etiopathogenesis of RA, we investigated the relationship of serological disease marker (RF, ERS, CRP and anti-CCP antibody) levels with arthritis severity (SJC28, TJC28, DAS28-ESR and pVAS), and hematological maker (lymphocytes, WBC and Hb) levels." (PMID 29408886, 2018). "This was not different for patients presenting with or without an elevated CRP, with or without subclinical MRI-detected inflammation and for patients who did or did not develop arthritis." (PMID 29724244, 2018). "Patients that presented with or without an elevated CRP, with or without subclinical MRI-detected inflammation or who did and did not develop arthritis did not have higher stress levels (p = 0.18, p = 0.83 and p = 0.60 respectively)." (PMID 29724244, 2018). "In addition, we also found that RFX1 expression level was negatively correlated with serum C-reactive protein (CRP) level, a surrogate marker of IL-6 activity, in SLE patients with active arthritis." (PMID 29422534, 2018). "After additional adjustments for CRP and anti-citrullinated protein antibody (ACPA) the results remained similar (β = 0.96, p = 0.003 for RA patients and β = 1.039, p = 0.043 for other early arthritis patients)." (PMID 27770823, 2016). "Interestingly, the ACG/Jacalin index had a higher correlation coefficient for joint parameters than CRP or MMP-3, suggesting that this index is a more specific arthritis marker." (PMID 27209430, 2016). "We observed a significant positive correlation between systemic 11β-HSD1 activity and ESR/CRP in patients with established RA but not in any of the early arthritis patients group." (PMID 25971255, 2015). "First, the results were based on the relatively robust laboratory values (i.e., CRP), semiobjective joint examinations, and ultrasound evidence of joint inflammation, which were all obtained by independent observers without knowledge of group allocation." (PMID 25614748, 2014). "On the other hand, it appears that alpha-1-antichymotrypsin (which did decrease in men but not women) can serve as a more sensitive marker to arthritis than measures such as C-Reactive Protein (which did not change in this investigation)." (PMID 21899733, 2011). "Synovial tissue was also obtained from two patients with quiescent RA (no swollen joints, CRP <3 mg/L) and from one patient who was unaffected by arthritis." (PMID 15540281, 2004). "Per ASAS, SpA features including IBP, arthritis, enthesitis (inflammation where a tendon attaches to bone), uveitis, dactylitis, psoriasis, IBD, good response to non-steroidal anti-inflammatory agents (NSAIDs), family history for SpA, HLA-B27, and elevated CRP." (PMID 40658153, 2025). "Also showed a significant increase (1200%) in the concentration of C- Reactive Protein (CRP) and (581%) sedimentation rate of red blood cells (Erythrocyte Sedimentation Rate (ESR)) at the level (P ≤ 0.001) in the serum of arthritis patient group compared to the control group." (PMID 38765271, 2024). "For example, a patient may experience improvement in their ESR one year after their severe arthritis resolved, but their CRP may not return to normal." (PMID 39767180, 2024). "The arthritis control group showed a significant increase in serum levels of RF, CRP, and ESR compared to the normal control group, and the treatment groups showed a significant decrease in serum levels of RF, CRP, and ESR compared to the arthritis control group." (PMID 39055869, 2024).